ERICH6 (glutamate rich 6)
Synonyms: C3orf44; FAM194A; MGC39662; ERICH6A
Tractability: No criterion of Open Targets' tractability assessment is met for any kind of drug.
Gene: Protein-coding gene on chromosome 3 (150,659,885 to 150,703,971, reverse strand). Ensembl gene ENSG00000163645.
Subcellular location: Nucleus
Gene Ontology:
Cellular component: nucleus
Genetic constraint (gnomAD): Loss-of-function variants: 58 observed, 62.91 expected, observed/expected ratio (o/e) 0.92, 90% interval 0.75 to 1.15. The upper end of that interval is the gene's LOEUF score, 1.15, which puts it in group 5 of 6, group 1 being the genes least tolerant of losing a copy. Missense variants: 775 observed, 797.41 expected, observed/expected ratio (o/e) 0.97, 90% interval 0.92 to 1.03. Synonymous variants: 255 observed, 282.16 expected, observed/expected ratio (o/e) 0.9, 90% interval 0.81 to 1.
Homologues: Orthologues: chimpanzee ERICH6 (99% identical), macaque ERICH6 (93% identical), dog ERICH6 (72% identical), pig ERICH6 (68% identical), rat Erich6 (60% identical), rabbit ERICH6 (59% identical), guinea pig ERICH6 (58% identical), mouse Erich6 (56% identical), tropical clawed frog ERICH6 (31% identical). Paralogues in human: ERICH6B (17% identical), FAM194C (13% identical).